CRP (C-reactive protein)
Diseases named in the same sentence as CRP in open-access papers (continued):
Sharing a sentence is not in itself a finding about the gene and the disease.
COVID-19 (continued). "Numerous studies have found that biomarkers such as ferritin and CRP are positively correlated with elevated pro-inflammatory cytokines and are linked to COVID-19 severity and mortality." (PMID 38178206, 2024). "C-reactive protein (CRP) was elevated in patients with COVID-19 associated with AKI (COVAKI) (78.87) but was statistically significant (p<0.003)." (PMID 38715992, 2024). "In this study, a decrease in C-reactive protein levels was associated with successful extubation in COVID-19 patients." (PMID 38597482, 2024). "Elevated CRP, a marker of inflammation, is frequently observed in severe COVID-19 cases and is linked to poor outcomes." (PMID 39338165, 2024). "There are several biomarkers associated with the severity of COVID-19, including C-reactive protein (CRP), D-dimer levels and troponin." (PMID 38792278, 2024). "The resulting model demonstrated that for every 10 mg/dL increase beyond the CRP reference value, the risk of death in COVID-19 patients increased by 7.3% (OR = 1.0073; CI = 1.002 to 1.01; p = 0.011)." (PMID 39335653, 2024). "Elevated CRP levels have been consistently associated with severe COVID-19 outcomes, including higher rates of hospitalization, progression to acute respiratory distress syndrome (ARDS), and mortality." (PMID 39408010, 2024). "C-reactive protein (CRP) is another relevant factor associated with the risk of ICU admissions for pregnant women infected with COVID-19." (PMID 39768627, 2024). "A study conducted in cancer patients indicated that higher COVID-19 severity was associated with abnormal CRP levels." (PMID 38433274, 2024). "The hospital treatment of patients with T2DM and a milder form of COVID-19 was associated with older age, the use of oxygen therapy, and elevated CRP values." (PMID 38792970, 2024). "The inflammatory hyperresponsiveness, defined by increased C-reactive protein (CRP), interleukin (IL)-6, and fibrinogen concentrations, observed during COVID-19 causes an increase in D-dimer levels." (PMID 40008234, 2024). "The length of hospitalization of T2DM patients with mild COVID-19 was associated with older age, the use of oxygen therapy, and elevated CRP values." (PMID 38792970, 2024). "Low diastolic blood pressure, tachypnea, hypoxia, high NLR, eosinopenia, high CRP, and isolation HD treatment were independently associated with mortality of COVID-19 in ESKD patients." (PMID 38807735, 2024). "Elevated CRP levels are a typical clinical manifestation of severe COVID-19, while normal or low levels of elevated CRP are seen early in infection caused by other respiratory viruses." (PMID 38623185, 2024). "Neutrophil–monocyte ratio, neutrophil–lymphocyte ratio, C‐ reactive protein, interleukin 6, and D-dimer were considered to be relevant factors associated with the death risk of COVID-19-related death by LASSO regression." (PMID 39555074, 2024). "Although CRP has been largely associated to poor COVID-19 outcomes, also independently of age, it is known to be affected by sex, age, and comorbidities." (PMID 39664394, 2024). "It is also responsible for a wide variety of pathological immunological phenomena associated with acute and post-acute COVID-19 and is associated with high levels of proinflammatory cytokines and inflammatory markers like CRP." (PMID 38610703, 2024). "Different scientific studies have identified certain risk factors for the severe evolution of COVID-19 in children, among which are young age; comorbidities; and elevated C-reactive protein, ferritin, and ALT values at hospitalization." (PMID 39768357, 2024). "In the current study, besides urine cadmium, we found that lymphopenia, thrombocytopenia, elevated LDH, and elevated CRP were all independently associated with severe COVID-19 in the multivariable regression models (all p < 0.05)." (PMID 38504259, 2024).
COVID-19 (continued). "Comparably, it has been demonstrated that C-reactive protein (CRP), which has a good diagnostic accuracy in identifying severe COVID-19, correlates with the severity of the disease and was markedly elevated in severe instances." (PMID 39599491, 2024). "It was determined that CRP rs1205 TT genotype (P < 0.0001, OR 9.74, 95% CI 7.87–12.06) was linked to a greater chance to COVID-19 mortality." (PMID 38184750, 2024). "In a meta-analysis investigating the association between clinical biomarkers like CRP, procalcitonin, serum ferritin, and D-dimer with the severity of COVID-19, all parameters were associated with severe disease and poor outcomes." (PMID 38562329, 2024). "High levels of C-reactive protein were associated with the development of severe COVID-19 stages and higher mortality." (PMID 38541668, 2024). "This is important because elevated levels of CRP are associated with a higher risk of complications, progression of disease, and worse prognosis in COVID-19 patients." (PMID 38687065, 2024). "This can lead to COVID-19-associated systemic inflammation and hypoxemic respiratory failure, as indicated by elevated blood levels of IL-6, C-reactive protein (CRP), D-dimer, and ferritin." (PMID 38251210, 2024). "Elevated CRP levels are associated with severe COVID-19 cases in pregnancy and have been linked with ICU admission, preterm labor, and poor maternal outcomes, as they reflect underlying inflammatory responses that are heightened in severe infections." (PMID 39768627, 2024). "After adjusting the impact of CRP rs1800947 polymorphism for SARS-CoV-2 variants, the COVID-19 mortality rate was correlated with CRP rs1800947 GG in the all three variants and with CRP rs1800947 CG genotype in the Alpha and Delta variants." (PMID 38184750, 2024). "Two studies published in Frontiers in Immunology highlight that elevated CRP levels are strongly associated with severe forms of COVID-19." (PMID 39055314, 2024). "Our research highlights the critical need for early blood sugar monitoring and using indicators such as HOMA-IR and hs-CRP to assess patients at risk of developing glycemic complications during COVID-19." (PMID 39595206, 2024). "The multivariate analysis with adjustment for potential confounding variables revealed that higher IL-34 and CRP levels were independently associated with COVID-19." (PMID 38626032, 2024). "A T-dominant genotype of rs1205 in the CRP gene is associated with COVID-19 death or hospitalization, even after adjustment for relevant clinical factors and potential participant relatedness." (PMID 38662664, 2024). "There was a significant association between COVID-19 severity and male gender, hypertension, diabetes mellitus, and high CRP." (PMID 38263160, 2024). "They trigger an increase in lymphocytes and a decrease in CRP correcting the decrease in lymphocytes and the increase in CRP caused by the COVID-19." (PMID 38836262, 2024). "This is consistent with other studies that report elevated IL-6, D-dimer, LDH, and CRP levels in severe COVID-19 cases, independently of specific viral mutations." (PMID 39861827, 2024). "CRP was associated with severe COVID-19 and is also considered a predictor of in-hospital mortality in the elderly." (PMID 39281667, 2024). "Our results clearly showed that a lower EPA/AA ratio, mainly observed in Groups 4–5, was associated with a higher concentration of IL-6 and CRP, typically elevated in critically ill COVID-19 patients, bringing a worse prognostic to these patients." (PMID 38702342, 2024). "In this study, patients with the CRP rs1800947 G allele had a significantly higher death rate from COVID-19." (PMID 38184750, 2024). "CRP, an acute phase reactant, is significantly increased in COVID-19 patients, indicating a strong association with poor prognosis." (PMID 38533136, 2024).
COVID-19 (continued). "Based on the presented results, the length of hospital treatment of patients with diabetes and a milder form of COVID-19 was associated with older age, the use of oxygen therapy, and elevated CRP values." (PMID 38792970, 2024). "According to our results, the COVID-19 mortality rate was correlated with CRP rs1800947 GG genotype in all three variants, as well as with CRP rs1800947 CG genotype in the Alpha and Delta variants of the gene." (PMID 38184750, 2024). "The genetically instrumented CRP showed only nominally significant associations, with ORs ranging from 1.31 to 1.60 for different COVID-19 datasets." (PMID 39062668, 2024). "Among biomarkers associated with COVID-19 severity, all the patients presented elevated CRP levels (>0.5 mg/dl), indicating the presence of an advanced inflammatory process at the time of admission." (PMID 38500972, 2024). "There was a significant difference between the recovered and the deceased patients in terms of the minor allele frequency of CRP rs1205 T and rs1800947 G. In all three variants, COVID-19 mortality rates were associated with CRP rs1800947 GG genotype." (PMID 38184750, 2024). "A high CRP level is associated with severe pneumonia in COVID-19 patients and is a predictor of deterioration to acute respiratory distress syndrome (ARDS) and death." (PMID 38982355, 2024). "According to existing guidelines, some clinical indicators such as CRP, D-dimer, ferritin, neutrophils, and chemokines are associated with the severity of COVID-19 and patient mortality rates." (PMID 39639868, 2024). "Our study further investigated serum levels of CRP, IL-1α, IL-6, and IL-10 as predictive markers for identifying patients at risk of worsening COVID-19." (PMID 39338474, 2024). "We observed that suPAR exhibited a more pronounced additive effect on the association between BMI and COVID-19 in-hospitalization outcomes compared with CRP and IL-6." (PMID 38635301, 2024). "In particular, high C-reactive protein (CRP) levels have been extensively described in COVID-19, being associated with worse prognosis, although it remains a marker with low specificity." (PMID 38700782, 2024). "CRP levels correlated with age in our cohort, and this observation was often reported in previous studies on COVID-19; also, higher CRP levels were confirmed to be associated with poor outcome in our setting." (PMID 38700782, 2024). "We sought to combine the abnormal fluctuations in the concentrations of four biomarkers associated with thrombosis in COVID-19: CRP, calprotectin, sP-selectin, and D-dimer." (PMID 39661669, 2024). "Our study underscores the significance of elevated serum CRP levels and the failure of CRP levels to decrease adequately by the third day; both were closely associated with respiratory deterioration in COVID-19 patients." (PMID 39685844, 2024). "In order to verify the utility of CRP polymorphism correlation in predicting COVID-19 mortality, a replication of these results is needed." (PMID 38184750, 2024). "Systemic inflammation evoked by SARS-CoV-2 is a hallmark of COVID-19, and one of the most widely used biomarkers for inflammation is an acute-phase protein CRP, which is biosynthesized in the liver in response to elevated interleukin-6 levels." (PMID 38570550, 2024). "For example, elevated inflammatory markers such as C-reactive protein (CRP) and procalcitonin have been associated with severe COVID-19 outcomes." (PMID 39144686, 2024). "Systemic inflammation, especially CRP > 40 mg/L35 and elevated interleukin-619 is a hallmark of severe disease with COVID-19." (PMID 38396069, 2024). "They found that high IL-6 levels, CRP and hypertension were independent risk factors of COVID-19 severity." (PMID 38099004, 2023). "Another limitation of our study is that high CRP concentration is considered both a nutritional prognostic marker and an associated factor of mortality for cancer and COVID-19 patients." (PMID 36946825, 2023).
COVID-19 (continued). "Deceased COVID-19 patients were shown to have higher levels of IL-6 and CRP and were associated to poor clinical outcome and severe organ failure." (PMID 37545721, 2023). "C-reactive protein (CRP) serum levels were associated with both overall and cause-specific mortality due to COVID-19 and digestive cancers in the Black group, where elevated CRP has previously been linked to psychosocial stress due to discrimination." (PMID 36963080, 2023). "Alterations of biomarkers in COVID-19 associated ischemic stroke included prolonged activated partial thromboplastin time and elevated CRP, fibrinogen and D-dimer levels, while data on LDH levels are divergent." (PMID 37231476, 2023). "In many different studies carried out so far, many parameters such as advanced age, high d-dimer, CRP levels and lymphopenia have been found to be associated with COVID-19 severity." (PMID 38223639, 2023). "The clinical risk factors associated with ischemic stroke in patients infected with COVID-19 are age, disease severity, cardiovascular risk factors, increased CRP, and increased D-dimer levels." (PMID 37092518, 2023). "Laboratory findings, such as elevated levels of D-dimer, lactate dehydrogenase (LDH), and C-reactive protein (CRP), have also been associated with poor disease progression in COVID-19." (PMID 37108026, 2023). "Further studies on larger cohorts should be conducted to assess the impact of age on the association between BMI, CRP, and risk of death due to COVID-19." (PMID 38003780, 2023). "Recently, CRP elevation was found to be associated with QTc interval prolongation in patients hospitalized with COVID-19." (PMID 37371071, 2023). "Predictive models for severe COVID-19 showed that CRP was associated with a higher chance of severe disease." (PMID 36687389, 2023). "Regarding multiple linear regression analysis in COVID-19, CRP, IL-6, and leucocytes (each p < 0.05) were associated with the degree of pulmonary infiltrates, as opposed to DPP3 (p = n.s)." (PMID 37733154, 2023). "The severity of COVID-19 is associated with interleukin-6 (IL-6), C-reactive protein (CRP), and other proinflammatory factors." (PMID 38110869, 2023). "Of the biomarkers of inflammation, the most evidential is the usefulness of CRP and D-dimer levels in predicting both the severity of COVID-19 and the risk of thrombotic complications." (PMID 37373613, 2023). "The stopping of physical activity was associated with increased BMI and CRP levels, lower vitamin D levels and a higher prevalence of post-COVID-19 fatigue, dyspnea, arthralgia, and myalgia." (PMID 37048602, 2023). "We also found robust new evidence that higher levels of inflammatory biomarkers (CRP, IL-6) at admission are associated with COVID-19-related death and disease severity." (PMID 37204441, 2023). "There was a significant reduction in eGFR after AKI due to COVID-19, being associated with age, length of hospital stay, CRP, and need for hemodialysis." (PMID 37311051, 2023). "We also underline that higher levels of inflammation markers (CRP, ferritine, D-dimer) correlate with the increased severity of COVID-19 and are associated with worse results in these patients." (PMID 36992258, 2023). "Though canonical markers of inflammation (IL-6, TNF-α, and CRP) have previously been shown to be associated with higher mortality in supercentenarians and COVID-19 patients, there is an intricate interplay between immune cells and cytokine secretion." (PMID 37928548, 2023). "Several studies have documented the association between COVID-19 severity and inflammatory and coagulation makers such as D-dimer, prothrombin time (PT) and C-reactive protein (CRP) as indicator of inflammation disorder and coagulopathy respectively." (PMID 37744945, 2023). "Numerous markers of inflammation have been associated with the clinical severity of COVID-19; higher values of IL-6, CRP, and D-dimer have been found in severe and critical forms of COVID-19." (PMID 37631910, 2023).
COVID-19 (continued). "Another study showed that decreased lymphocyte count and increased ALT, AST, and CRP were linked with clinical unimprovement of COVID-19 patients in hospitals." (PMID 38152668, 2023). "Aspartate aminotransferase (AST) and C-reactive protein (CRP) are markers of liver damage and inflammation, and both are linked with poor COVID-19 prognosis (13, 48, 56, –, 58)." (PMID 37681966, 2023). "In other COVID-19 studies, an upregulation in Ferritin and CRP in COVID-19 cases was associated with poor clinical prognosis." (PMID 38057707, 2023). "Consistent with previously identified prognostic factors of COVID-19, CRP level and lymphocyte percentage were associated with unfavorable treatment responses in this analysis." (PMID 37762792, 2023). "Previous research has shown that increased inflammation, as indicated by elevated CRP levels, is associated with worse clinical outcomes in COVID-19 patients." (PMID 37265905, 2023). "Increased levels of pro-inflammatory cytokines and the inflammatory marker CRP were linked to systemic inflammation in COVID-19 patients." (PMID 37674675, 2023). "Our results demonstrated that clinical features such as ESR and CRP levels showed a significant association with patterns of change in consolidation on CXR determined by AI in COVID-19 patients." (PMID 37370985, 2023). "The ROC curve shows that the highest WBC and high D-dimer are more sensitive to diagnosing severe unstable COVID-19 with good diagnostic performance than CRP and high ferritin with fair to poor diagnostic performance." (PMID 37235308, 2023). "The ROC analysis suggested that MDW is a superior predictor of severity, WBC count and CRP level as a diagnostic predictor of COVID-19." (PMID 36973757, 2023). "Similar to COVID-19 associated PE and DVT, data of laboratory parameters revealed elevated D-dimer and CRP levels in most COVID-19 associated CVT cases." (PMID 37231476, 2023). "Higher CRP levels were associated with aggravated COVID-19 cases, and these levels occurred before disease progression." (PMID 37643201, 2023). "In support of the relationship between type II and III IFNs, we recorded a dysregulation in IFNγ and IFNλ gene expression levels in those patients with changed LDH, CRP and D-dimer values, which are known inflammatory markers associated with COVID-19 severity." (PMID 36985262, 2023). "Following adjustment for age, baseline CRP, ethnicity, and COVID-19 variant, there was a significant difference in progression to respiratory failure or death in response to treatment between males and females (p = 0.05)." (PMID 37598275, 2023). "PCT and CRP were also significantly associated with severe disease progression in one of the first COVID-19 studies." (PMID 37937220, 2023). "First of all, CRP is normally lacking in viral infections; however, the macrophage activation syndrome which characterizes COVID-19 causes the pro-inflammatory hypercytokinemia profile which results in increasing the CRP synthesis by hepatocytes." (PMID 37388734, 2023). "The systemic inflammation and cytokine storm typical of COVID-19 have been linked to an increase in levels of inflammatory biomarkers such as IL-6 and C-reactive protein (CRP)." (PMID 37637608, 2023). "Serial change in CRP levels from admission is associated with escalations of inpatient care intensity and mortality among hospitalized patients with COVID-19." (PMID 37934759, 2023). "Compared to other common respiratory viral infections, patients with COVID-19 had a higher incidence and severity of blood clotting, usually associated with higher levels of D dimer, C-reactive protein, P-selectin and fibrinogen." (PMID 37367410, 2023). "Here, we characterized the cellular origin of PS-exposing EVs in plasma from COVID-19 patients as well as their association with inflammation- and coagulation-related parameters, including CRP, HMGB-1, PF4, and TF." (PMID 38069209, 2023).